PDGFRA (platelet derived growth factor receptor alpha)
Diseases named in the same sentence as PDGFRA in open-access papers (continued):
Sharing a sentence is not in itself a finding about the gene and the disease.
tumor (continued). "Notably, we confirmed that monitoring of known KIT or PDGFRA mutations in plasma with ddPCR is useful in a bigger subset of GIST patients, and that might predict tumor progression before radiological evaluation." (PMID 32024476, 2020). "In this paper, we have presented a novel mathematical model of the co-evolution of three distinct tumour cell sub-populations to investigate the nature of interactions between cells with two common mutations occurring in GBMs, namely amplification of the genes encoding the EGFR and PDGFRA proteins." (PMID 33120534, 2020). "Our results show that a subset of GISTs WT for KIT and PDGFRA, including their largest pathogenetically characterized subpopulation, i.e., the SDH-deficient ones, is significantly enriched in MGMT-methylated cases, with SDH-deficient GISTs featuring the highest prevalence of this tumor variant." (PMID 30616628, 2019). "The oncogenic reliance of GISTs upon mutated KIT/PDGFRA is emphasized by their sensitivity to imatinib mesylate (IM), a tyrosine kinase inhibitor (TKI) that targets both KIT and PDGFRA kinase activity, leading to substantial tumor shrinkage with durable responses in most patients." (PMID 30867899, 2019). "It is possible that tumor initiation in utero with these genetic alterations or in a different cell-of-origin postnatally may obviate the requirement for PDGF-A ligand (or other similar genetic alteration such as mutant PDGFRA)." (PMID 30833574, 2019). "It has been suggested that the gene expression signature may not be due to the specific histone mutation, but rather the accompanying alterations (PDGFRA vs. ACVR1), supporting the notion that modulation of the microenvironment by tumour cells is more influential than the histone mutation." (PMID 30453529, 2018). "Therefore, targeting VEGFR2 and PDGFRα should preferentially target the tumor." (PMID 30050899, 2018). "Finally we show that fully blocking PDGFRA signaling impedes murine KS tumor formation." (PMID 29985958, 2018). "Since Lrat can only be expressed in HSCs and not in CAF, it can be speculated that PDGFRα expression in HCC might be associated with increased recruitment of HSCs in the tumor site." (PMID 28465473, 2017). "These activated HSCs might contribute PDGFRα over-expression in HCC tumor sites." (PMID 28465473, 2017). "While we did not see differences in ETV4 expression by tumor site (gastric versus small bowel) or mutation status (PDGFRa versus Kit), though the sample sizes were small for meaningful comparisons, most low-risk, human, primary, untreated GISTs had minimal or undetectable ETV4 expression." (PMID 29371979, 2017). "In order to evaluate whether PDGFRα expression on tumor site has association with genes for liver fibrosis or cancer-associated fibroblast, freshly frozen HCC specimens with matching non-tumor sites were used for mRNA quantification." (PMID 28465473, 2017). "It is tempting to speculate that SDH deficiency in the tumor may have contributed to the lack of response to this selective PDGFRA inhibitor." (PMID 28768491, 2017). "Our observations provide strong evidence that TAS-115 can serve as a multiple tyrosine kinase inhibitor which can impede c-MET and PDGFRα signalling and may offer the distinct clinical advantages even when used as a monotherapy for patients with SS tumours driven by either c-MET or PDGFRα pathways." (PMID 28511645, 2017). "However, insufficient frequency of YWHAE, NUTM2A, and NUTM2B gene rearrangement and absence of mutation in both the c-kit and PDGFRA genes suggested that this tumor should be categorized as epithelioid leiomyosarcoma." (PMID 28288693, 2017). "Importantly, we find that these results are translatable to therapeutic ATM inhibition in human patient-derived GBM stem cells, and that combining ATM inhibition with PDGFRA inhibition results in synergistic tumor cell killing with minimal effects on untransformed cells." (PMID 26984279, 2016).
tumor (continued). "We now provide the first evidence that Hedgehog developmental signaling is present in the ICC lineage and is dysregulated in GIST, irrespective of KIT/PDGFRA mutations or tumor location, adding Hedgehog to the growing list of developmental signaling pathways important in GIST." (PMID 27793025, 2016). "Moreover, PTX3, COLEC12 and PDGFRA genes were found as possible candidates for biomarkers of ATC while GPR110 could be tested to distinguish PTC over other tumor subtypes." (PMID 25887408, 2015). "Furthermore, the primary duodenal GIST was reevaluated as borderline nature and no KIT and PDGFRA mutation was found in the tumor." (PMID 23902675, 2013). "In comparison, the role of PDGFRA has been much less appreciated, although there is evidence to suggest that signalling through the receptor plays an important role in regulating VEGF-driven tumour angiogenesis particularly when tumour cells are deficient in VEGF production." (PMID 23990986, 2013). "Estimated 1-year PFS and 2-year OS according to primary tumor genotype were as follows: KIT exon 9 mutations - 68%/73% (median 65.5/151.5 weeks), wild type - 57%/70% (median 50.5/121 weeks), KIT exon 11 mutations - 34%/34% (median 36.8/65.5 weeks) and PDGFRA mutations - 15%/25% (median 9/40 weeks)." (PMID 22439647, 2012). "Therefore, it is possible that claudin-low tumors present with elevated levels of PDGFRα and PDGFRβ, a characteristic that may improve the treatment of this class of tumor." (PMID 22070644, 2011). "Platelet-derived growth factors (PDGFs) and their tyrosine kinase receptors (PDGFRA and B) play essential roles in stimulating cell growth and differentiation, and these molecules have been demonstrated to be involved in growth stimulation of tumor cells, tumor angiogenesis and invasiveness." (PMID 21466706, 2011). "By simultaneously inhibiting VEGFR, FGFR, PDGFRα, RET, and KIT, LEN effectively blocks tumor angiogenesis and tumor progression, leading to potent antitumor effects." (PMID 41155549, 2025). "All PDGCAs expressed markers of tumor epithelial and stem cells (EPCAM, CDH1, KRT18, CA9, CD24, CD133), stromal and extracellular matrix components (COL3A1, COL5A1, DCN, PDGFRA, and PDGFRB), and mesenchymal stem cells (CD73, CD105, CD90)." (PMID 40723172, 2025). "Immunostaining confirmed that both tumor types were OLIG2+, suggesting that tumors formed from aberrant expansion of PDGFRA+ OPCs." (PMID 40060572, 2025). "Conversely, while KIT mutant cases showed an equal distribution in primary tumor site, NF1-mutant cases had an exclusive small intestine localization (9/9), and PDGFRA-mutant cases had gastric localization only (18/18)." (PMID 41407759, 2025). "It exerts its antitumor activity by inhibiting multiple receptor tyrosine kinases, including KIT, PDGFRA, PDGFRB, VEGFRs, RET and FLT3, thereby targeting both tumor cell proliferation and angiogenesis." (PMID 40733131, 2025). "Lenvatinib is a multi-targeted tyrosine kinase inhibitor that significantly inhibits tumor angiogenesis and tumor cell proliferation by targeting signaling pathways such as VEGFR1-3, FGFR1-4, PDGFRα, RET and KIT." (PMID 41451007, 2025). "Integrin αvβ1 on CAFs participates in the fibrillar fibronectin assembly of CAFs via PDGFRα, and in myosin light chain 2 (MLC2) contractility and traction forces, which then induces directional mobility of tumor cells." (PMID 40352270, 2025). "Amplification of the PDGFRA gene locus is a common event in GBM, promoting tumor development and progression." (PMID 40565099, 2025). "Subgroup 3 and 7 expressed inflammatory subtypes such as CFD, PDGFRA and DCN, and the remaining tumour cells expressing inflammatory markers were named iCAF." (PMID 39789383, 2025). "The “platelet-derived growth factor binding” and “insulin-like growth factor binding” signatures were among the top signatures enriched and the respective genes PDGFRβ, PDGFRα, and IGFL1 were among the top-enriched genes in mCAFhighendotheliahigh tumor niches." (PMID 41083996, 2025).
tumor (continued). "It works by slowing down or stopping the growth of tumor cells through the inhibiting tyrosine kinases, including KIT and PDGFRα." (PMID 40696704, 2025). "Our findings corroborate the role of PDGFRA in HCC resistance to lenvatinib across cellular, organoid, as well as in vivo xenograft and orthotopic HCC tumor models in mice." (PMID 40336047, 2025). "Resistance alterations were evident in the recurrent tumor: high-level PDGFRA amplification (111 copies) and an in-frame MDM2::PDGFRA fusion – exon 1 of MDM2 (NM_001145339.2, breakpoint 15 bp into exon 1) joined in-frame to exon 8 of PDGFRA (NM_006206.6)." (PMID 40819143, 2025). "This phenomenon involves the transcriptional silencing of tumor suppressor genes (including BRCA1/BRCA2, TP53BP1, SMAD4) and the abnormal activation of oncogenes (such as PDGFRA, PIK3CA, and BRAF), thereby facilitating tumor initiation and progression." (PMID 40927709, 2025). "Of the non-KIT non-PDGFRA mutated tumor samples, no models could be established." (PMID 39853155, 2025). "Surveying the Xenium probe-based in situ sequencing and imaging data, we found high agreement between three cell type markers (ERBB2-tumor, PTPRC-immune, and PDGFRA-stroma) and our CTA outcomes, suggesting its robustness for detecting FFPE sections as well." (PMID 40925915, 2025). "We found patients with higher CAF-FAP (FAP+VIM+) at tumor core or lower CAF-C7 (PDGFRA+VIM+) at tumor margin exhibited worse survival (tumor core, n = 154, P = 0.036; tumor margin, n = 148, P = 0.037)." (PMID 39870619, 2025). "We initially selected tumor tissues from HCC patients to establish PDX models and assessed PDGFRA expression levels in the primary tumor tissues using immunohistochemical staining." (PMID 40336047, 2025). "Genetic aberrations, including PDGFRA, MYCN, and CDK4 amplifications alongside CDKN2A/B deletions, facilitate tumor advancement." (PMID 40927709, 2025). "In a co-culture assay, T cells, in the presence of PDGFRα/β+PDPN (podoplanin) + CAFs, exhibited low cytotoxicity towards co-cultured tumour cells." (PMID 39780187, 2025). "PDGFRa activates the PI3K/MAPK and PI3K/AKT signaling pathways and enhances proliferation, migration, and survival of tumor cells." (PMID 41009560, 2025). "We and others have previously shown that the PDGFRA and FGFR1 RTKs are important for the survival of malignant rhabdoid tumour cells and complete suppression of PDGFRA is necessary to achieve cell death." (PMID 40781553, 2025). "Amplification of PDGFRα is a characteristic feature of the proneural subtype of GBM, playing a crucial role in cell proliferation and tumor cell signaling." (PMID 40332008, 2025). "Further enrichment analysis revealed that iCAF enriched chemokines, TGFβ, ECM, IL6 pathway, PDGFRA pathway, inflammatory response, hypoxia, tumor angiogenesis, and VEGF signaling pathway, which are crucial for tumor progression, metastasis, and immune escape." (PMID 40525824, 2025). "The aim of this study was to investigate the expression of PDGFRα and PDGFRβ in RCC cells and assess their impact on tumor growth characteristics and patient prognosis." (PMID 40434293, 2025). "Of note, those groups of FOXL2+COL1A1+ cells, besides positivity for COL1A1, had higher expression of αSMA, PDGFRa, and FAP (frame 2) than FOXL2+COL1A1− tumor cells themselves (frame 1)." (PMID 41042551, 2025). "The identification of clonal subpopulations that express different RTKs (EGFR, PDGFRA, and MET) in a mutually exclusive manner fuelled interest into characterising intra-tumour heterogeneity in GBM." (PMID 39816516, 2025). "In this tumor, copy number variation (CNV) analysis showed that MDM4 amplification dominates the malignant clones, which additionally have either EGFR or PDGFRA amplifications, resulting in increased ChrAcc around these genes." (PMID 38724668, 2025). "Summary of existing guidelines for recommendations of SDHB immunohistochemistry (IHC) and molecular tumor analysis, and timing in relation to KIT/PDGFRA testing." (PMID 39927693, 2025).
tumor (continued). "Most of anlotinib’s targets were upregulated in DDLPS, while FGFR1, PDGFRA and PDGFRB were significantly upregulated in tumor tissues." (PMID 39117615, 2024). "Circulating tumor DNA testing at the onset of the second episode of DIC revealed high levels of androgen receptor, CCND1, and PDGFRA gene amplification." (PMID 39764338, 2024). "PDGFRA is often amplified in DIPG and its expression is particularly prominent in oligodendrocyte precursor–like (OPC-like) cells, a key tumor-propagating cell compartment." (PMID 38488006, 2024). "Anti-PDGFRα antibody, olaratumab, was found to have promising results in GBM xenografts, significantly inhibiting tumour growth in vivo with a concomitant reduction in PDGFR phosphorylation." (PMID 38615034, 2024). "Two sets of genes were chosen, PDGFRA, Lin28A, THBS1, JUN, PLCB1 and GABRA5, which were found to be up- and down-regulated, respectively, in support of tumour cell proliferation." (PMID 38000389, 2024). "Descriptive data for tumor expression of c-Kit, VEGFR2, PDGFRα, PDGFRβ between different histological subtypes in the 96 pediatric patients with NRSTS." (PMID 39534097, 2024). "This block in differentiation allows tumor cells to maintain an open chromatin landscape at enhancers such as GSX2, which are then hijacked by the overexpressed PDGFRA gene." (PMID 39202398, 2024). "Overall, 32.3% demonstrated high expression of PDGFRα, 17.7% for PDGFRβ, 19.8% for VEGFR2 and 8.3% exhibited positive expression for c-kit on the tumor cells." (PMID 39534097, 2024). "Further multivariate analysis unveiled significant insights: LRP1, PAEP, PI3, OBP2A, and IL27RA genes exhibited higher levels in the tumour group, whereas FOS, PDGFRA, and FGF7 showed higher expression in normal ovarian tissue (all p < 0.001)." (PMID 39063239, 2024). "The copy numbers of shared CNVs, such as PDGFRA/KIT, CDK4, MYC, KRAS, and VEGFR2, were highly consistent (Pearson correlation = 0.95, P = 0) between the CSF and tumor tissues." (PMID 38388726, 2024). "Tumor cells were immersed in a dense stromal ECM, as suggested by the relevant expression of Desmin, αSMA, Collagen I, PDGFRα and Vimentin." (PMID 38338669, 2024). "Imatinib mesylate (STI571), is a selective kinase inhibitor that inhibits the activation of ALB, KIT, PDGFRA, and PDGFRB, thereby inhibiting tumor growth." (PMID 39600645, 2024). "High PDGFRA and PDGFC expression can promote tumor proliferation, angiogenesis, migration, and invasion." (PMID 36979654, 2023). "Recently, our group reported a case of PDGFRA-mutant GIST with ALK expression, in which the tumor had an immense size, and follow-up revealed liver metastases that developed quickly." (PMID 37120571, 2023). "tumor and ascitic fluid were positive for CD44, and weak expression of CAFs (PDGFRα, FAP) was observed." (PMID 37958844, 2023). "T cells cocultured in KC or 4KC PDGFRα+ CAF-conditioned medium showed proliferation and GrzB production similar to those cultured in control conditioned medium obtained from tumor cells alone." (PMID 38111825, 2023). "As demonstrated by our findings, ECM-modulating genes, such as MMP2 and MMP14, were clearly upregulated in the CAFs, and CAFs were found to secrete PDGFRA and CXCL12, which promote tumor progression, further validate the accuracy of CAF classification." (PMID 37565899, 2023). "Platelet-derived growth factor receptor alpha (PDGFR-α, encoded by PDGFRA) was specifically expressed in fibroblasts but not in other cell types, but since it was expressed in fibroblasts of both normal tissues and tumor tissues, thus it could be used as a pan-fibroblast marker." (PMID 36744260, 2023).
tumor (continued). "Immunohistochemical analysis of metastatic nodules in both lung and liver tissues from CRC and PDAC tumor‐bearing mice showed that metastases in Bmal1−/− mice were enriched in stromal fibroblasts that were positive for FAP, α‐SMA, DESMIN, PDGFRα, and PDGFRβ." (PMID 37330661, 2023). "Stromal PDGFRα signaling disrupts ECM homeostasis during mammary gland development, leading to increased mammary gland stiffness and increased tumor growth potential." (PMID 37745843, 2023). "Immunohistochemistry analysis of metastatic nodules demonstrated marked mitigation of the FAP+, α‐SMA+, DESMIN+, PDGFRα+, and PDGFRβ+ fibrotic components in TGF‐βR1‐treated Bmal1−/− tumor‐bearing mice." (PMID 37330661, 2023). "Cell line and original tumor share the majority of CNV alterations, including losses in Chr 9/10 that included PTEN and MGMT and gains in Chr 20, which included amplification of PDGFRA, CDK4, and MDM2." (PMID 37958846, 2023). "MGMT methylation analysis was performed on 68 tumour samples from 65 individual patients including 47 wtGIST (67.7%) and 21 (32.3%) TK mutant (17 KIT and 4 PDGFRA) GIST (30.9%)." (PMID 36198483, 2023). "Compared with normal fibroblasts, cancer-associated fibroblasts express increased markers, such as FAP, PDGFRα, and αSMA, which have been used as biomarkers to isolate CAF population from the tumor tissue." (PMID 35155261, 2022). "Using our fusion gene database, we identified gene–gene fusions in cfDNA and tumour DNA, such as KDR‐PDGFRA (8%), and NCDN‐PDGFRA (40%) that correspond to the previously reported alterations of PDGFRA in GBM (43% of all our samples)." (PMID 34875133, 2022). "In previous work, we showed that silencing of SH3BP2 diminished KIT, PDGFRA, and MITF levels lead to a reduction in tumor growth in vitro and in vivo." (PMID 36551682, 2022). "Within tumor regions, we used markers informed by scRNA-seq analysis to identify CAF1 (SMA and VIM) or CAF2 (TNC and PDGFRα) populations." (PMID 35600339, 2022). "Our bioinformatic analysis showed that tumor angiogenesis-related proteins, including EGFR, FGF1, FGF2, VEGRR2, and PDGFRA, were in the top 15 key targets in the PPI network of QDSJ decoction treating NF2-associated VS." (PMID 36059985, 2022). "The genes TNR, OLIG1, and PDGFRA are specific to the OPC cluster and are differentially expressed in tumor and periphery cells." (PMID 35327982, 2022). "In tumor specimens from CRC patients, PDGFRα/β expression correlates with lymphatic dissemination and metastasis." (PMID 36614038, 2022). "The activation of the cell surface protein kinases PDGFRA, PDGFRB and EGFR promotes cell proliferation in normal cells and is enhanced in certain tumour types, while their down-regulation is in accord with the cell cycle inhibition we uncovered." (PMID 35205253, 2022). "Although as one might expect, more mutations were detected in the tumor tissue, including MTOR and BRCA1; however, the pathogenic PDGFRA variant (c.1939A > G, p.Ile647Val) was found in the urinary exosomes from both UC and NanoPoms preparations, but not in the tumor tissue cells." (PMID 35787656, 2022). "For example, among 10 markers that are localized in the tumor stroma according to IHC images, 4 genes (MFAP2, MFAP5, PDGFRA, CDH11) are specifically represented in “Fibroblasts”, while the remaining markers are expressed in both cell types." (PMID 36263012, 2022). "As previously observed in vitro, pladienolide B administration in vivo significantly decreased various relevant tumor progression markers and critical oncogenic spliceosome components (VEGFA/EGFR/CDK4/PDGFRA/PDGFRB and SRSF3/PTBP1)." (PMID 35086552, 2022).